CDC7 (cell division cycle 7)
Description:
Kinase involved in initiation of DNA replication. Phosphorylates critical substrates that regulate the G1/S phase transition and initiation of DNA replication, such as MCM proteins and CLASPIN.
Synonyms: HsCdc7; huCdc7; CDC7L1; Hsk1
Tractability: Small molecule: a drug acting on it is in phase 2 or 3 trials; a structure with a bound ligand is known; a high-quality ligand is known; it belongs to a druggable protein family. PROTAC: it is named in the literature on targeted protein degradation; UniProt records ubiquitination sites on it; ubiquitination databases record sites on it; a small molecule that binds it is known.
Target class: Other protein kinase group; Enzyme; Protein Kinase; Other protein kinase CDC7 family; Kinase
Chemical probes: CHEMBL2348154, NMS-354, PD070157, PD070158, PD070159, PD070160, PD070162, PD070166, PD070167, PD070173, PD070174, PD070175, PD070176, PD070178, PD070180, PD070181, PD070182, PD070186, PD070187, PD070189, and 7 more
Gene: Protein-coding gene on chromosome 1 (91,500,535 to 91,527,360, forward strand). Ensembl gene ENSG00000097046.
Subcellular location: Nucleus
Subcellular location (Human Protein Atlas): Nucleoplasm; Cytokinetic bridge; Mitotic spindle
Pathways (Reactome):
Cell Cycle: Activation of ATR in response to replication stress
DNA Replication: Activation of the pre-replicative complex
Gene expression (Transcription): Transcriptional Regulation by E2F6
Gene Ontology:
Molecular function: kinase activity; protein binding; protein kinase activity; protein serine kinase activity; ATP binding; protein serine/threonine kinase activity
Biological process: cell cycle phase transition; positive regulation of cell population proliferation; positive regulation of G2/M transition of mitotic cell cycle; positive regulation of nuclear cell cycle DNA replication; double-strand break repair via break-induced replication; G1/S transition of mitotic cell cycle; mitotic DNA replication checkpoint signaling; mitotic intra-S DNA damage checkpoint signaling
Cellular component: cytoplasm; Dbf4-dependent protein kinase complex; intercellular bridge; mitotic spindle; nucleoplasm; nucleus
Genetic constraint (gnomAD): Loss-of-function variants: 19 observed, 31.35 expected, observed/expected ratio (o/e) 0.61, 90% interval 0.42 to 0.89. The upper end of that interval is the gene's LOEUF score, 0.89, which puts it in group 3 of 6, group 1 being the genes least tolerant of losing a copy. Missense variants: 427 observed, 520.11 expected, observed/expected ratio (o/e) 0.82, 90% interval 0.76 to 0.89. Synonymous variants: 162 observed, 175.21 expected, observed/expected ratio (o/e) 0.92, 90% interval 0.81 to 1.05.
Homologues: Orthologues: chimpanzee CDC7 (99% identical), macaque CDC7 (97% identical), dog CDC7 (91% identical), pig CDC7 (88% identical), guinea pig CDC7 (86% identical), rabbit CDC7 (83% identical), rat Cdc7 (79% identical), mouse Cdc7 (79% identical), tropical clawed frog cdc7 (56% identical), zebrafish cdc7 (47% identical), Drosophila melanogaster Cdc7 (32% identical), Drosophila melanogaster CG5790 (30% identical), and 1 more. Paralogues in human: CSNK1D (15% identical), CSNK1E (15% identical), CSNK1A1L (14% identical), CSNK1G3 (14% identical), CSNK1G2 (14% identical), CSNK1A1 (14% identical), CSNK1G1 (14% identical), TTBK1 (13% identical), TTBK2 (12% identical), VRK1 (12% identical), VRK2 (10% identical), VRK3 (9% identical).
Diseases named in the same sentence as CDC7 in open-access papers:
CDC7 is named in the same sentence as 67 diseases in open-access papers, as found by Europe PMC text mining. Sharing a sentence is not in itself a finding about the gene and the disease. The quoted sentences say what the papers report.
breast carcinoma (16 papers, 2011 to 2024). "Of the key genes unique to basal-like breast cancer, the expression levels of only CDC7, KIF18A, STIL, and CKS2 were associated with patient survival time (P < 0.05)." (PMID 33066779, 2020). "Additional studies are needed to determine the molecular basis of the interaction between GLIS2 and CDC7 as well as the role of rs13447455 in breast cancer susceptibility." (PMID 30823486, 2019). "The functional polymorphism on CDC7, rs13447455, influences CDC7 transcriptional activity in an allele-specific manner and alters DNA–protein complex formation in breast cancer cell lines." (PMID 30823486, 2019). "In agreement with our results, increased CDC7 expression was linked to loss of tumor differentiation, genomic instability and development of aggressive phenotype in breast cancer." (PMID 29339028, 2019). "Whereas in CRC low levels of Cdc7 expression were significantly associated with high tumor grade and stage, in breast cancer high levels of Cdc7 expression were linked with higher tumor grade and stage." (PMID 26208856, 2015). "Though previous studies had reported the impact of CDC7 on multiple cancers, the other two genes and the lncRNA are novel in relation to genetic predisposition to cancer, with the potential to be new targets in the treatment and prevention of breast cancer." (PMID 35708873, 2022). "One study showed increased CDC7 mRNA level in malignant transformed breast cancer cell line and also in hyper-proliferating cells in a lesser degree in comparison with primary normal cells." (PMID 29339028, 2019). "In another recent study of our group on more than 2.100 breast cancers, Cdc7 expression was seen in 57 % of the cases." (PMID 26208856, 2015). "We screened a panel of 15 breast cancer cell lines for Cdc7 and Dbf4 expression using monoclonal antibodies against each subunit." (PMID 25412417, 2014). "CDC7 is overexpressed in many human tumor cell lines and tissues, such as ovarian cancer, colorectal cancer, lung cancer, salivary gland malignant tumor, and breast cancer." (PMID 33763482, 2021). "Additionally, silencing of cell cycle-regulatory or transcriptional CDKs in combination with a cdc7-specific inhibitor (XL413) in breast cancer cells has been shown to mimic the cell cycle disruption caused by PHA-767491." (PMID 31262335, 2019). "Next, in relation to an in-house cohort of lymph node-negative, non-(neo) adjuvantly treated 123 oestrogen receptor-negative (ER-neg) breast cancer patients, high expression of cdc7 was significantly associated with a poor metastasis-free survival (MFS)." (PMID 31262335, 2019). "Overexpression of Cdc7 and its protein regulator Dbf4 has been reported in many human tumors, including ovarian cancer, melanoma, diffuse large B-cell lymphoma, oral squamous cell carcinoma and breast cancer." (PMID 26208856, 2015).
breast carcinoma (continued). "Epigenetic MR analysis identified four CpG sites, cg03260624 near CDC7 gene, cg10816169 near ZNF318 gene, cg03345232 near RIN3 gene, and cg26312998 near RP11-867G23.13 gene, where genetically predicted epigenetic modifications were associated with an increased breast cancer incidence risk." (PMID 35708873, 2022). "Moreover, high expression of cdc7 and RNA polymerase II Subunit A (POLR2A), the direct target of CDK9, is significantly correlated with poor metastasis-free survival in a cohort of breast cancer patients." (PMID 31262335, 2019). "Although the IHC scoring system was slightly different in this breast cancer study (4 categories vs 3 categories ), the percentages of Cdc7 negative, weakly and strongly positive breast cancers were similar to our findings in CRC." (PMID 26208856, 2015). "Compared to HME cells, geminin, TopoIIα, Cdc7 and CKIε proteins are overexpressed in several estrogen receptor (ER)-positive breast cancer cell lines (for example, MCF7 and BT474) as well as ER-negative breast cancer cell lines (for example, MDAMB231, MDAMB453 and SKBR3)." (PMID 21595939, 2011).
colorectal cancer (11 papers, 2009 to 2025). A primary or metastatic malignant neoplasm that affects the colon or rectum. "We discovered that, in patients with colorectal cancer, CDC7 expression was linked to tumor recurrence and a poor prognosis." (PMID 40136426, 2025). "CDC7 (Cell Division Cycle 7), is an important gene, found highly expressed in a number of cancers including colorectal cancer." (PMID 30150654, 2018). "This suggests that targeting CDC7 may be a potentially viable treatment for people with colorectal cancer." (PMID 40136426, 2025). "Finally, our findings strongly argue for a clinical utility of Cdc7 immunostaining as an independent prognostic biomarker in colorectal cancer enabling to select patients for adjuvant treatment." (PMID 26208856, 2015). "Little is known about the prevalence and significance of Cdc7 in colorectal cancer." (PMID 26208856, 2015). "Moreover, our findings strongly argue for a clinical utility of Cdc7 immunostaining as an independent prognostic biomarker in colorectal cancer enabling to select patients for adjuvant treatment." (PMID 26208856, 2015). "Our data show that Cdc7 is expressed in the majority of colorectal cancers and therefore could serve as a potential therapy target." (PMID 26208856, 2015).
liver cancer (10 papers, 2019 to 2025). An epithelial or non-epithelial malignant neoplasm that arises from the liver. "Subsequently, cells were treated with mTOR suppressors, which caused an apoptosis of CDC7 inhibitor-treated liver cancer cells." (PMID 36232388, 2022). "Similar to CDC7 inhibition, treatment with cisplatin synthesizes liver cancer cells to AZD6738, further supporting the relation between DNA replication stress and the sensitivity of ATR or CHK1 inhibitors." (PMID 34663432, 2021). "Our data highlights the potential of targeting ATR-CHK1 signaling, either alone or in combination with CDC7 inhibition, for the treatment of liver cancer based on the level of replication stress." (PMID 34663432, 2021). "Our data highlights the potential of targeting ATR-CHK1 signaling, either alone or in combination with CDC7 inhibition, for the treatment of liver cancer." (PMID 34663432, 2021). "When we inhibited CDC7 in liver cancer cells with the CDC7 inhibitor XL413, we observed strong suppression of its downstream target p-MCM2 at XL413 concentrations of 5 μM to 10 μM." (PMID 34663432, 2021). "Targeting cdc7 was also considered to block cell proliferation of liver cancer cells." (PMID 36430192, 2022). "By screening 149 pairs of liver cancer specimens in the GEO database GSE76297, we found that CD47 and CDC7 were highly expressed in cancer tissues." (PMID 38520730, 2024). "The sequential release of a senescence inducer (CDC7 inhibitor) and a CD47 inhibitor from the dual‐targeting nanosystem in situ induced senescence and antitumor immune responses to aganist liver cancer and overcome chemoresistance." (PMID 38520730, 2024). "An additional analysis of five pairs of liver cancer specimens (GSE146049) confirmed that CD47 and CDC7 were highly expressed in HCC tissues." (PMID 38520730, 2024). "Overall, the nanosystem in this work achieved the sequential release of CDC7 and CD47 inhibitors in situ to trigger senescence and induce immunotherapy, effectively combating liver cancer and overcoming chemoresistance." (PMID 38520730, 2024). "For liver cancer cells that are resistant to ATR or CHK1 inhibition, treatment with CDC7 inhibitors induces strong DNA replication stress and consequently such drugs show striking synergy with ATR or CHK1 inhibitors." (PMID 34663432, 2021). "Interestingly, we discovered that miR‐191 strongly and positively correlated with several important cell cycle regulators, including CDC25A, CDC7 and CDCA8 in the TCGA liver cancer database." (PMID 31334580, 2019). "Moreover, CD47 is highly expressed, and senescence is inhibited after the development of chemoresistance, suggesting that combination therapy targeting CD47 and CDC7 to inhibit CD47 and induce senescence may be a promising strategy for liver cancer." (PMID 38520730, 2024). "Here, patients with liver cancer co‐expressing CD47 and CDC7 (cell division cycle 7, a negative senescence‐related gene) are found to have the worst prognosis." (PMID 38520730, 2024).
ovarian cancer (8 papers, 2018 to 2025). A primary or metastatic malignant neoplasm involving the ovary. "CDC7 encodes for a cell division cycle protein and has been found to both predict survival and be a powerful anticancer target in ovarian cancer." (PMID 31060502, 2019). "DBF4 encodes for a protein that activates the kinase activity of CDC7 and was found to be associated with ovarian cancer." (PMID 31060502, 2019). "To further compare our results to existing biological knowledge, we found evidence in the literature that CDC7, ORC6L, and DBF4 are associated specifically with ovarian cancer." (PMID 31060502, 2019). "Additionally, the overexpression of CDC7 has been verified in various types of cancers including central nervous system cancer, colon cancer, lung cancer, leukemia, kidney cancer, ovary cancer, prostate cancer and breast cancer." (PMID 30150654, 2018). "Many other genes in the cell cycle pathway, such as CDC7, CDK1 and CHEK1, have previously been reported to be correlated with the proliferation and chemoresistance of ovarian cancer." (PMID 34876569, 2021).
lung carcinoma (7 papers, 2014 to 2024). "In summary, SMC6, CDC27, CDC7, RACGAP1, SMC4, NCF1,2,4, SELPLG and CFP are significantly associated with T2DM and lung cancer, making them potential target genes for disease prediction and treatment in the future." (PMID 38468345, 2024). "Barkley proposed that miR-29a targets the 3-UTR of DBF4 mRNA in lung cancer cells and Bonte stated that most cell lines with increased Cdc7 protein levels also had increased DBF4 abundance, and some tumor cell lines had extra copies of the DBF4 gene." (PMID 25866773, 2015). "Mimicking the results observed in lung cancer, analysis of a publicly available transcriptomic dataset of human PRAD22 revealed increased CDC7 mRNA expression on those PRAD exhibiting NE features, and consistently, NEPC PDX exhibited higher CDC7 protein expression than those derived from PRAD." (PMID 39054323, 2024).
hepatocellular carcinoma (6 papers, 2018 to 2025). A malignant tumor that arises from hepatocytes. "The Belgian group’s “one-two punch” strategy “CDC7 inhibitor-induced senescence” + “mTOR blocker-triggered apoptosis” effectively eliminated hepatocellular carcinoma cells with improved patient tolerance compared to conventional cytotoxic therapies." (PMID 40801613, 2025). "Specifically, CDC7 inhibitors have first been used to induce senescence of hepatocellular carcinoma cells, followed by sertraline application to induce apoptosis of the senescent cells." (PMID 32991321, 2020). "Following the synthesis of CCNB1, CDC20, CDC7, BUB1B, and MCM3 have been examined in hepatocellular carcinoma (HCC) samples." (PMID 36497125, 2022).